RNU6-110P (RNA, U6 small nuclear 110, pseudogene)
Gene: Small nuclear RNA gene on chromosome 1 (25,964,197 to 25,964,300, forward strand). Ensembl gene ENSG00000207237.
Homologues: Orthologues: chimpanzee U6 (99% identical), macaque U6 (90% identical), guinea pig U6 (82% identical), pig U6 (80% identical). Paralogues in human: RNU6-20P (91% identical), RNU6-25P (90% identical), RNU6-38P (90% identical), RNU6-73P (90% identical), RNU6-1 (89% identical), RNU6-1145P (89% identical), RNU6-2 (89% identical), RNU6-35P (89% identical), RNU6-39P (89% identical), RNU6-3P (89% identical), RNU6-41P (89% identical), RNU6-434P (89% identical), and 1287 more.